MIR194-2 (microRNA 194-2)
Synonyms: hsa-mir-194-2; MIRN194-2; mir-194-2
Gene: MicroRNA gene on chromosome 11 (64,891,355 to 64,891,439, reverse strand). Ensembl gene ENSG00000284155.
Gene Ontology:
Biological process: miRNA-mediated post-transcriptional gene silencing
Cellular component: RISC complex